DPEP2 (dipeptidase 2)
Description:
Dipeptidase that hydrolyzes leukotriene D4 (LTD4) into leukotriene E4 (LTE4). Hydrolyzes cystinyl-bis-glycine. Independently of its dipeptidase activity can also modulate macrophage inflammatory response by acting as a regulator of NF-kappaB inflammatory signaling pathway.
Synonyms: MBD2
Tractability: Small molecule: it belongs to a druggable protein family. Antibody: UniProt predicts a signal peptide or a membrane-spanning region; its Gene Ontology location is reachable by antibodies, with medium confidence. PROTAC: its protein half-life has been measured.
Gene: Protein-coding gene on chromosome 16 (67,987,392 to 68,000,615, reverse strand). Ensembl gene ENSG00000167261.
Subcellular location: Membrane
Pathways (Reactome):
Metabolism: Aflatoxin activation and detoxification; Synthesis of Leukotrienes (LT) and Eoxins (EX)
Disease: LTC4-CYSLTR mediated IL4 production
Gene Ontology:
Molecular function: dipeptidase activity; exopeptidase activity; metallodipeptidase activity
Biological process: leukotriene D4 catabolic process; leukotriene metabolic process; proteolysis
Cellular component: membrane; plasma membrane
Genetic constraint (gnomAD): Loss-of-function variants: 45 observed, 52.98 expected, observed/expected ratio (o/e) 0.85, 90% interval 0.67 to 1.09. The upper end of that interval is the gene's LOEUF score, 1.09, which puts it in group 4 of 6, group 1 being the genes least tolerant of losing a copy. Missense variants: 604 observed, 636.21 expected, observed/expected ratio (o/e) 0.95, 90% interval 0.89 to 1.01. Synonymous variants: 255 observed, 257.77 expected, observed/expected ratio (o/e) 0.99, 90% interval 0.89 to 1.1.
Homologues: Orthologues: chimpanzee DPEP2 (99% identical), macaque DPEP2 (94% identical), pig DPEP2 (77% identical), dog DPEP2 (75% identical), mouse Dpep2 (71% identical), rat Dpep2 (70% identical), mouse Dpep2 (69% identical), rabbit DPEP2 (68% identical), tropical clawed frog dpep2 (44% identical), zebrafish dpep2 (43% identical), Drosophila melanogaster CG44837 (39% identical), Drosophila melanogaster CG6154 (37% identical). Paralogues in human: DPEP3 (70% identical), DPEP1 (38% identical).
Diseases named in the same sentence as DPEP2 in open-access papers:
DPEP2 is named in the same sentence as 27 diseases in open-access papers, as found by Europe PMC text mining. Sharing a sentence is not in itself a finding about the gene and the disease. The quoted sentences say what the papers report.
diabetes (2 papers, 2024). "IGLJ3, DNASE1L3, ABCG1, DPEP2, and KIF19 are highly differentiated genes associated with diabetes and periodontitis." (PMID 38532421, 2024).
lung adenocarcinoma (2 papers, 2023). A carcinoma that arises from the lung and is characterized by the presence of malignant glandular epithelial cells. "Considering the relationship between the risk model and the presence of immune infiltration, and immunotherapy, we further explored the possible roles of the two genes used to construct the model: BTK and DPEP2 genes in the tumor microenvironment of lung adenocarcinoma." (PMID 36991102, 2023). "Given that lung adenocarcinoma (LUAD) is the most common subtype of NSCLC, our study aimed to examine the expression and function of DPEP2 in LUAD." (PMID 37375818, 2023).
myocarditis (2 papers, 2019 to 2023). Myocarditis is a condition that is characterized by inflammation of the heart muscle (myocardium). "Cardiac-infiltrating macrophages express upregulated levels of dipeptidase 2 (Dpep2) during myocarditis." (PMID 37175422, 2023). "In this study, we found that cardiac Dpep2 expression was significantly increased in the CVB3-induced myocarditis, indicating that Dpep2 participated in the disease development." (PMID 30899700, 2019). "Here, we found that cardiac Dpep2 expression was significantly increased in CVB3-induced myocarditis, suggesting its possible involvement in VMC." (PMID 30899700, 2019). "However, whether Dpep2 was involved in CVB3-induced myocarditis was still unknown." (PMID 30899700, 2019). "Our findings might shed light on the pathogenesis of CVB3-induced myocarditis, and may provide a potential treatment strategy for VMC based on manipulating macrophage Dpep2 expression." (PMID 30899700, 2019). "This might explain why the increased Dpep2 expression in the whole heart tissue did not efficiently repress the overproduction of pro-inflammatory cytokines in CVB3-induced myocarditis." (PMID 30899700, 2019). "This inspired us that abundant macrophage Dpep2 at the early stage of VMC might be important for controlling massive cardiac inflammation, and ensuring competent Dpep2 in macrophages might represent a novel therapeutic strategy against CVB3-induced myocarditis." (PMID 30899700, 2019).
periodontitis (2 papers, 2024 to 2025). An acute or chronic inflammatory process that affects the tissues that surround and support the teeth. "Other significant genes included DNASE1L3, CDKL1, and DPEP2, highlighting the compounding effects of poor glycemic control, dyslipidemia, and periodontitis on molecular dysregulation." (PMID 40458179, 2025).
Sepsis (2 papers, 2025). Sepsis is defined as life-threatening organ dysfunction caused by a dysregulated host response to infection. "Moreover, macrophage-specific Dpep2 deficiency increased the serum concentrations of inflammatory cytokines, higher reactive oxygen species (ROS) production and shortened overall survival in the LPS-induced model of sepsis." (PMID 40021897, 2025). "Dipeptidase-2 (DPEP2) is increasingly recognized for its role in lipid metabolism, sepsis, and AF, primarily functioning through the regulation of inflammation and cell signaling." (PMID 41359645, 2025). "In sepsis, DPEP2 is closely related to macrophage function, and its deficiency leads to excessive production of pro-inflammatory factors (such as TNF-α and IL-6), highlighting its importance in inhibiting macrophage overactivation and maintaining immune homeostasis." (PMID 41359645, 2025). "Further analysis of the correlation between sepsis feature genes and immune cells revealed that CLU, GLPX, and CKAP4 were negatively correlated with CD4 naive T cells, while DPEP2 and BCL11B were positively correlated." (PMID 41359645, 2025). "Ultimately, by taking the intersection of the results from the three machine learning methods, we identified six feature genes in sepsis: CD81, CLU, GLRX, CKAP4, DPEP2, and BCL11B; and seven feature genes in atrial fibrillation: LDHB, CD81, PFKFB2, CKAP4, CXCR4, DPEP2, and RORA." (PMID 41359645, 2025).
viral myocarditis (2 papers, 2019 to 2023). Myocarditis that is caused by an infection with a viral agent. "The protein expression of DPEP2, a dipeptidase involved in leukotriene metabolism, was recently found as a modulator of macrophage inflammatory responses, protecting mice against Coxsackievirus B3-induced viral myocarditis." (PMID 37228491, 2023).
AIDS (1 paper, 2022). A syndrome resulting from the acquired deficiency of cellular immunity caused by the human immunodeficiency virus (HIV). "We screened four immune cell-related genes, ARRB1, DPEP2, LTBP3, and RGCC, which may be considered as the diagnostic markers for HIV-1/AIDS." (PMID 36123690, 2022).
arachnoid cyst (1 paper, 2019). Intracranial or spinal cavities containing a cerebrospinal-like fluid, the wall of which is composed of arachnoidal cells. "Recent studies showed that Dpep2 expression altered in the temporal fossa arachnoid cysts, implying that Dpep2 might be involved in the inflammatory responses." (PMID 30899700, 2019).
atrial fibrillation (1 paper, 2025). A disorder characterized by an electrocardiographic finding of a supraventricular arrhythmia characterized by the replacement of consistent P waves by rapid oscillations or fibrillatory waves that vary in size, shape and timing and are accompanied by an irregular ventricular response. "In the atrial fibrillation dataset, LDHB, PFKFB2, CKAP4, CXCR4, DPEP2, and RORA genes showed an upregulation trend, while only the CD81 gene was downregulated in the disease group." (PMID 41359645, 2025). "In the selection of feature genes for atrial fibrillation, LDHB, DPEP2, BCL11B, CKAP4, RORA, PFKFB2, and CXCR4 were identified as potentially important predictors, with the model error being lowest when the number of genes reached eleven." (PMID 41359645, 2025). "In the immune cell correlation analysis of atrial fibrillation feature genes, we observed that CXCR4 was negatively correlated with regulatory T cells and Macrophages M2, while LDHB was positively correlated with gamma delta T cells, and DPEP2 was positively correlated with CD8 T cells." (PMID 41359645, 2025).
endometriosis (1 paper, 2025). The growth of functional endometrial tissue in anatomic sites outside the uterine body. "Another enriched pathway across the four conditions is ‘arachidonic acid metabolism’; of the five endometriosis genes enriched in this pathway, four are shared with the other three immune conditions, namely, DPEP3, GPX1, DPEP2, and PON2." (PMID 40262193, 2025).
HIV-1 infection (1 paper, 2022). The type species of lentivirus and the etiologic agent of acquired immunodeficiency syndrome (AIDS). "As the best model for diagnosing HIV-1±, RF was used to select four critical immune cell-related genes, namely, ARRB1, DPEP2, LTBP3, and RGCC, and a nomogram model was created to predict the occurrence of HIV-1 infection based on four key immune cell-related genes." (PMID 36123690, 2022).
lung squamous cell carcinoma (1 paper, 2023). "Our analysis revealed that DPEP2 expression was significantly lower in many malignant tumors, particularly in LUAD and lung squamous cell carcinoma (LUSC), than in normal tissues." (PMID 37375818, 2023).
type 2 diabetes (1 paper, 2022). "The protein encoded by DPEP2 has been shown to modulate macrophage inflammation, and is upregulated in subcutaneous white adipose tissue in obese women with type 2 diabetes." (PMID 35665255, 2022).
cancer (5 papers, 2023 to 2024). A tumor composed of atypical neoplastic, often pleomorphic cells that invade other tissues. "We retrieved data from the TIMER database to investigate the expression of DPEP2 in pan-cancer." (PMID 37375818, 2023). "Similarly, GO analysis illuminated the role of genes in the negative regulation of peptidase activity, with studies indicating Dipeptidase-2's impact on E-cadherin levels, affecting cell migration, cancer stem cell dynamics, and drug resistance, which in turn affects the survival of LUAD patients." (PMID 38849442, 2024). "Moreover, other metabolic proteins were highly elevated in CRC patients including HAGH and DPEP2 which may reflect the metabolism reprogramming due to CRC tumorigenesis, a well-known hallmark of cancer." (PMID 37228491, 2023).
tumor (5 papers, 2022 to 2025). "Furthermore, our hypothesis was further validated by GSE162669 analysis, which showed that the expression of DPEP2 was significantly lower in tumor-associated macrophages than in alveolar-associated macrophages." (PMID 37375818, 2023). "Furthermore, our hypothesis was further validated by GSE162669 analysis, which showed that the expression of DPEP2 was significantly lower in tumor-associated macrophages compared to alveolar-associated macrophages." (PMID 37375818, 2023). "Furthermore, we discovered that DPEP2 was more abundantly expressed in cell clusters of normal tissue origin versus primary tumor tissue or distant metastatic tissue origin." (PMID 37375818, 2023). "We hypothesize that BTK and DPEP2 genes may alter the immune microenvironment of tumors by affecting the function of macrophages and the anti-tumor therapeutic effect, which deserves further research." (PMID 36991102, 2023). "Considering the critical role of inflammation and immunity in LUAD, more clinical samples and animal models will be required to unravel the specific potential mechanisms in which DPEP2 participates, particularly in regulating immune cells and inflammation in the tumor microenvironment." (PMID 37375818, 2023). "Taken together, this evidence suggests that DPEP2 might partially act as a tumor suppressor in LUAD cells." (PMID 37375818, 2023). "The results imply that BTK and DPEP2 may regulate the abundance of immune infiltration and promote anti-tumor immunity by affecting the function of macrophages and monocytes." (PMID 36991102, 2023). "Based on bioinformatics and the analysis of clinical samples, our findings revealed that DPEP2 is highly expressed in normal lung tissues, but downregulated in LUAD tissues, and its expression levels were significantly associated with clinical indicators of tumor grade and prognosis." (PMID 37375818, 2023). "Furthermore, we postulate that the impact of DPEP2 on the LUAD tumor microenvironment may be influenced by specific cell types or immune environments." (PMID 37375818, 2023). "Through the analysis of LUAD single-cell transcriptome datasets, the Tumor Immune Estimation Resource (TIMER), TISIDB, and other databases, we found that DPEP2 plays a pivotal role in shaping the immune microenvironment of LUAD." (PMID 37375818, 2023). "It was found that tumor tissues had lower expression of BTK and DPEP2 at mRNA and protein levels compared to normal tissues." (PMID 36991102, 2023). "As expected, the TIMER database showed a significant positive correlation between BTK and DPEP2 expression and immune cell infiltration and a significant negative correlation with tumor purity." (PMID 36991102, 2023). "Next, LUAD samples were divided into high and low DPEP2 expression groups based on DPEP2 expression levels, with the goal of determining whether the different DPEP2 expression groups differed in terms of the abundance of 22 immune cells in the immune microenvironment of an LUAD tumor." (PMID 37375818, 2023).
infection (2 papers, 2017 to 2019). The state of being infected such as from the introduction of a foreign agent such as serum, vaccine, antigenic substance or organism. "Considering that the increase of cardiac Dpep2 appeared on day 3 post-infection, at that time cardiac macrophages began to enrich and represent the primary infiltrating inflammatory cells, so we considered macrophages as one of candidates." (PMID 30899700, 2019). "We found that after infection, Dpep2 was significantly increased in macrophages but not in the infected cardiomyocytes, which lasted to day 7 post-infection." (PMID 30899700, 2019).
inflammation (2 papers, 2019 to 2025). Aberrant reaction of the microcirculation characterized by movement of fluid and leukocytes from the blood into extravascular tissues. "Interestingly, macrophage-specific Dpep2 deletion robustly aggravated CVB3-induced cardiac inflammation, evidenced by augmented expression of TNF-α, IL-6, and MCP-1 in heart tissue." (PMID 30899700, 2019).
DPEP2 also shares sentences with these, for which no sentence is quoted: asthma (1 paper); colorectal adenocarcinoma (1); colorectal cancer (1); colorectal tumor (1); dyslipidemia (1); intestinal inflammation (1); lung carcinoma (1); Obesity (1); ovarian serous cystadenocarcinoma (1); thyroid abnormality (1).